CDKN2A (cyclin dependent kinase inhibitor 2A)
Diseases named in the same sentence as CDKN2A in open-access papers (continued):
Sharing a sentence is not in itself a finding about the gene and the disease.
serous ovarian carcinoma (2 papers, 2008 to 2015). "We have previously documented the utility of Nutlin-3a in low-grade serous ovarian carcinoma, with up-regulation of cell cycle control, and apoptosis genes including CDKN1A, CDKN2A, PERP, and PUMA." (PMID 26248031, 2015).
spindle cell tumor (2 papers, 2023 to 2025). "CDKN2A, the gene encoding the cell cycle checkpoint protein P16, is considered a tumor suppressor gene and can be up-regulated or down-regulated in different tumors, with P16 also expressed in various other spindle cell tumors." (PMID 38239634, 2023). "In summary, we reported the first case of primary pancreas NTRK-rearranged spindle cell tumor with a special sclerosing epithelioid fibrosarcoma pattern harboring EVT6::NTRK3 gene fusions, CDKN2A/2B homozygous deletion, and ARID1A mutation." (PMID 40548109, 2025).
thoracic tumors (2 papers, 2023 to 2025). "Therefore, MTAP immunohistochemistry has been demonstrated to potentially represent a valuable FISH surrogate for the identification of CDKN2A HD in PM,14, 21, 22, 23 as also specified in the 2021 WHO Classification of Thoracic Tumours." (PMID 40566743, 2025).
thyroid (2 papers, 2013 to 2020). "Particularly in PTC, p16INK4a, and p14arf coded by CDKN2A were both identified to be upregulated in thyroid tumorigenesis." (PMID 33553144, 2020).
transitional cell papilloma (2 papers, 2020 to 2021). A benign papillary neoplasm composed of transitional cells which show preservation of the nuclear polarity. "CDKN2A showed high level of expression (301.31, 2078.34, and 555.12 fold) in transitional papilloma RT4 cells, HT1197 cells, and 253JB-V cell line whereas J82 cells showed down-expression 0.5 fold at p-value 0.000." (PMID 34885040, 2021).
uterine corpus endometrial carcinoma (2 papers, 2020 to 2025). A endometrial carcinoma (disease) that involves the body of uterus. "The one exception to this relationship is in uterine corpus endometrial carcinoma (UCEC), where RB1 mutations and CDKN2A mutations are co-occurring." (PMID 32242058, 2020).
22q11.2 deletion syndrome (1 paper, 2024). 22q11.2 deletion syndrome (DS) is a chromosomal anomaly which causes a congenital malformation disorder whose common features include cardiac defects, palatal anomalies, facial dysmorphism, developmental delay and immune deficiency. "Most cases are sporadic but rare cases have been described in neurofibromatosis type 1 (NF1), Down syndrome (trisomy 21), DiGeorge syndrome (22q11.2 deletion syndrome), Sturge-Weber syndrome (somatic GNAQ variants) and familial melanoma-astrocytoma syndrome (CDKN2A/B loss)." (PMID 39294363, 2024).
alpha-thalassemia/mental retardation syndrome X-linked (1 paper, 2019). "Nevertheless, PDCLs preserved the main genomic aberrations found in patient tumors, including histone, ATRX (alpha-thalassemia/mental retardation syndrome X-linked) mutations, and CDKN2A (cyclin-dependent kinase inhibitor 2A) homozygous deletion." (PMID 31779235, 2019).
atrophic gastritis (1 paper, 2025). "Beyond the morphologic changes, atrophic gastritis with intestinal metaplasia is characterized by a progressive increase in CpG island methylation (“methylation index”) and promoter hypermethylation of key genes such as CDH1, CDKN2A (p16), and RUNX3." (PMID 41479890, 2025).
Atypical Meningioma (1 paper, 2022). A WHO grade II meningioma characterized by the presence of an increased mitotic activity or at least three of the following morphologic features: small cells, high cellularity, prominent nucleoli, lack of architectural pattern, and necrosis. "Furthermore, dysregulation of p16, CDK6, and pRB protein have all been associated with recurrence in atypical meningiomas and homozygous deletions of the CDKN2A/B gene has also been associated with early meningioma recurrence." (PMID 35936751, 2022).
bile duct cancer (1 paper, 2024). "Cyclin-dependent kinase inhibitor 2A (CDKN2A) is a suppressor carcinogenic gene that is upregulated across various types of cancer including breast, liver, thyroid, and bile duct cancer due to its crucial role in cell cycle regulation and cell division." (PMID 38894777, 2024).
bowel cancer (1 paper, 2023). "In summary, our findings suggest that the rs10811661 polymorphism of the CDKN2A / B gene is strongly associated with the occurrence of intestinal cancer and stomach is linked to its potential role as a prognostic biomarker for the management of bowel cancer and stomach." (PMID 37845622, 2023).
brain astrocytoma (1 paper, 2023). A astrocytoma (excluding glioblastoma) that involves the brain. "This study correlated MRI features with CDKN2A/B status, IDH mutation type and survival in histological grade 2-3 IDH-mutant brain astrocytomas." (PMID 37316586, 2023).
Brain atrophy (1 paper, 2018). Partial or complete wasting (loss) of brain tissue that was once present. "Cdkn2a transcript level, a hallmark measure of senescence, directly correlated with brain atrophy and NFT burden in mice." (PMID 30126037, 2018). "Further, when plotted against brain weight, Cdkn2a expression was a strong predictor of brain atrophy across mouse lines (p < 0.0001, R2 = 0.5615)." (PMID 30126037, 2018).
breast DLBCL (1 paper, 2023). "The most frequently observed mutations in breast DLBCL were CDKN2A and CDKN2B loss, which was found simultaneously in five of seven cases." (PMID 37706649, 2023). "In breast DLBCL, MYD88L265P (57.1%), CD79B mutation (42.9%), and CDKN2A/B loss (71.4%) were found at high frequencies, which were similar to the mutation patterns of DLBCL of immune‐privileged sites compared with DLBCL NOS." (PMID 37706649, 2023).
cartilaginous tumours (1 paper, 2015). "We show that p16/CDKN2A copy number variation occurs subsequent to the IDH1 mutation, and confirm that p16/CDKN2A copy number variation occurs in 75 % of high grade central chondrosarcomas, and not in low grade cartilaginous tumours." (PMID 25432631, 2015).
childhood leukemia (1 paper, 2023). An acute or chronic leukemia that occurs during childhood. "Therefore, mutations in CDKN2A (− 222 T>A) and CDKN2B (593A>T, C) may play a role in susceptibility to childhood leukemia." (PMID 37314514, 2023).
chondroid chordoma (1 paper, 2023). A slow-growing malignant bone tumor arising from the remnants of the notochord and occurring in the base of the skull. "Clinical relevance of CDKN2A expression and deletion of this gene locus were specifically address in the other study on classical and chondroid chordomas." (PMID 37434245, 2023).
CNS DLBCL (1 paper, 2021). "Although not included in this study, our NGS results for CNS DLBCL had a higher 9p21 (including CDKN2A and CDKN2B) loss ratio (13/17, 76.5%) than DLBCL NOS (43/154, 27.9%)." (PMID 34461835, 2021).
conjunctival intraepithelial neoplasia (1 paper, 2008). "The aim of our study was to identify the frequency of expression of p16INK4a (CDKN2A) and HPV (human papilloma virus) in different grades of conjunctival intraepithelial neoplasia (CIN)." (PMID 19516893, 2008).
coronary artery calcification (1 paper, 2012). Calcification of the coronary artery, used as a measure of coronary atherosclerosis, a risk factor for myocardial infarction. "In parallel, the CDKN2A/B locus has been strongly associated with coronary artery calcification, which was not investigated in this study." (PMID 22403661, 2012).
cutaneous malignant melanoma-3 (1 paper, 2021). "Although the etiology of the disease is fully complex including different types of genomic alteration in some genes, e.g. MC1R, CDKN2A, and CDK4, nonfunctional CDK4 is the cardinal hallmark of the disease cutaneous malignant melanoma-3 (CMM3)." (PMID 34735543, 2021).
cystadenoma (1 paper, 2024). A benign or borderline cystic epithelial neoplasm arising from the glandular epithelium. "Concordantly, other research has correlated KRAS and CDKN2A pathway alterations withmucinous cystadenomas and borderline tumors." (PMID 39040449, 2024).
duodenal cancer (1 paper, 2021). "A recent study on genomic variants demonstrated that CDKN2A/B and ERBB2/HER2 variants are more enriched in duodenal cancer than in small-bowel cancer and duodenal cancer overall tends to have lower TMB." (PMID 34014970, 2021).
eccrine adenocarcinoma (1 paper, 2024). "One other patient had a clear ARID1A loss on IHC: a patient with eccrine adenocarcinoma with ARID1A stop-gain mutation (R693X, resulting in truncated protein expression) and H score of 0 with CDKN2A deletion (240 mg BD; SD, 34 weeks)." (PMID 37934611, 2024).
embryonal carcinoma (1 paper, 2010). A non-seminomatous malignant germ cell tumor characterized by the presence of large germ cells with abundant cytoplasm resembling epithelial cells, geographic necrosis, high mitotic activity, and pseudoglandular and pseudopapillary structures formation. "Both LOHs of the CDKN2A were found in nonseminomas with a yolk sac tumor component, one sample also having an embryonal carcinoma component." (PMID 22933911, 2010). "Both LOHs of the CDKN2A were found in nonseminomas with a yolk sac tumor component, and both LOHs of the RB1 were found in nonseminomas with an embryonal carcinoma component." (PMID 22933911, 2010).
Endocrine Neoplasia (1 paper, 2025).
endometrioid endometrial carcinoma (1 paper, 2022). "However, CDKN2A upregulation may enhance autophagy in non-endometrioid endometrial carcinoma, which protects cells against unfavourable conditions, promoting tumorigenesis." (PMID 35459137, 2022).
epithelioid mesothelioma (1 paper, 2022). "Demonstration of loss of BAP1 or MTAP by immunohistochemistry, or CDKN2A homozygous deletion by FISH, is valuable in establishing the diagnosis of epithelioid mesothelioma." (PMID 36552912, 2022).
gallstones (1 paper, 2021). Solid crystalline precipitates in the biliary tract, usually formed in the gallbladder, resulting in the condition of cholelithiasis.
gastrointestinal polyp (1 paper, 2025). A polypoid tumor that arises from any part of the gastrointestinal tract and protrudes into the lumen. "Moreover, the CDKN2A gene is not typically involved somatically in gastrointestinal polyps, as seen in our patient." (PMID 40917369, 2025).
giant cell glioblastoma (1 paper, 2022).
giardiasis (1 paper, 2024). An infection of the small intestine caused by the flagellated protozoan giardia lamblia. "In this study, we demonstrated that the mean relative expression of the CDKN2A gene in people with a history of giardiasis is more than the expression of this gene in healthy people." (PMID 38170269, 2024). "Examining the mean expression of the four genes AKT1, CDKN2A, KRAS, and PIK3CA showed that three genes of AKT1, CDKN2A, and KRAS had increased expression in people with a history of giardiasis compared to healthy people." (PMID 38170269, 2024).
gliomatosis cerebri (1 paper, 2023). A diffuse glial tumor which infiltrates the brain extensively, involving more than two lobes. "In Case 2 with H3K27M-mutated DMG (and BRAFV600E and SMARCB1 alterations), and Case 3 with gliomatosis cerebri (EGFR overexpression and CDKN2A deletion) in reduced clinical condition, local re-irradiation and targeted therapy (with or without chemotherapy and/or immunotherapy) were proposed." (PMID 36720762, 2023).
glomerulonephritis (1 paper, 2013). A renal disorder characterized by damage in the glomeruli. "The covariates were based on CDKN2A and the stronger clinical univariate predictors: ECD and presence or absence of glomerulonephritis in the recipient." (PMID 23861858, 2013).
granulosa cell tumor (1 paper, 2023). A slow-growing, malignant tumor, characterize by the presence of granulosa-like cells and Call-Exner bodies, that is almost always found in the ovary.
heart tumors (1 paper, 2024).
hereditary tumor syndrome (1 paper, 2023). "This study investigates melanoma pancreatic syndrome, a rare hereditary tumor syndrome associated with CDKN2A gene mutations." (PMID 38137564, 2023).
Hypercalcemia (1 paper, 2024). An abnormally increased calcium concentration in the blood. "Herein, we describe a case of BCR-ABL positive ALL with a triploid karyotype, WT1, and CDKN2A mutations with hypercalcemia and bone destruction as the first manifestations." (PMID 38450181, 2024).
hypercortisolemia (1 paper, 2025). "The variant in CDKN2A gene (c.146T>C, p.Ile49Thr) was identified in a 15-year-old boy with CD who presented with a microadenoma (4 mm) and typical features of hypercortisolemia." (PMID 40813536, 2025).
hyperparathyroidism (1 paper, 2025). Hyperfunction of the parathyroid glands resulting in the overproduction of parathyroid hormone. "Hyperexpression of miR-24 inhibits production of parathyroid hormone by binding CDKN1B/p27, CDKN2A/p16, TGFβ1, and CASP8 transcripts, which are involved in the development of hyperparathyroidism." (PMID 40217882, 2025).
hypopharyngeal tumors (1 paper, 2016). "Although not identified in hypopharyngeal tumors, we could confirm CDKN2A mutations as second most frequent mutations overall in HPV-negative HNSCCs." (PMID 27528217, 2016).
infections in the skin (1 paper, 2016). "More interesting, we found five genes (CDKN2A, COL8A2, RASSF6, TMC4, and TMC5) from our 145 genes are associated with Walt’s disease (corrected P-value = 0.0040), which are infections in the skin caused by the human papillomavirus (HPV)." (PMID 27830726, 2016).
intestinal type adenocarcinoma (1 paper, 2021). An adenocarcinoma arising from epithelium which has undergone intestinal metaplasia.
keloid (1 paper, 2017). An irregularly shaped, elevated mark on the skin caused by deposits of excessive amounts of collagen during wound healing. "It meant, transcriptional levels of three array-up-regulated lncRNAs and three of their paired Wnt-genes, named CACNA1G-AS1/MMP2, HOXA11-AS/CDKN2A and LINC00312/KRT14, were significantly changed in keloids by intracellular qPCR measurement, simultaneously." (PMID 28404955, 2017).
latent infection (1 paper, 2021). "This is consistent with previously reported roles of the CDKN2A/CCND1/CDK4 axis in NPC cell growth and persistent EBV latent infection in NPE cells." (PMID 34234122, 2021).
lung mucinous adenocarcinoma (1 paper, 2024). "The loss of function mutation of NKX2-1/CDKN2A can induce tumor development in patients with KRAS-G12D mutation in lung mucinous adenocarcinoma." (PMID 38817907, 2024).
lung mucoepidermoid carcinoma (1 paper, 2023). "H292 cells are obtained from metastatic lung mucoepidermoid carcinoma, a cancer that originates in the salivary glands lining the tracheobronchial tree of the lung and is characterized by CDKN2A mutations." (PMID 38132948, 2023).
malignant epithelial ovarian tumours (1 paper, 2025). "In fact, this study primarily focused on p14, another product of the CDKN2A locus, and demonstrated the differential expression of this protein in benign, borderline, and malignant epithelial ovarian tumours." (PMID 39941911, 2025).
medullary carcinoma (1 paper, 2021). "In radiation-induced medullary carcinoma in 4W rats, the expression of Cdkn2a and Cxcr4 increased, whereas that of seven autophagy regulatory genes (Dapk1, Eif2ak3, Gaa, Hgs, Mapkl4, Mapt, and Pim2) and five autophagy machinery components (Atg4b, Atg5, Gabarapl2, Rab24, and Wipi1) decreased." (PMID 34580369, 2021).
meningeal cancer (1 paper, 2023). "However, it remains unclear whether CDKN2A abnormalities and MET amplification are involved in the process of brain metastasis of LUAD and how it affects the prognosis of meningeal cancer patients." (PMID 36937524, 2023).
Merkel cell carcinomas (1 paper, 2016). "The cell cycle pathway (CDKN2A/B, CDKN2C or RB1 genes) was also abnormal in 71% of patients (12/17) with Merkel cell carcinomas." (PMID 26981779, 2016).
metastatic colorectal cancer (1 paper, 2022). "Another study showed that CDKN2A may lead to the downregulation of the immune response and enhance the recurrence risk of metastatic colorectal cancer." (PMID 35429970, 2022).
myeloid neoplasm (1 paper, 2020). Proliferation of myeloid cells originating from a primitive stem cell. "The genetic profile of these MYC- translocated T-ALL is characterized by concomitant abnormalities, including CDKN2A/B deletions, PTEN inactivation, and mutations typical of myeloid neoplasms, such as DNMT3A." (PMID 32185137, 2020).
myocardial ischemia (1 paper, 2025). A disorder of cardiac function caused by insufficient blood flow to the muscle tissue of the heart. "ANRIL has been shown to regulate its neighboring Cyclin Dependent Kinase Inhibitor genes, CDKN2A and ‐B, but little is known about their role in myocardial ischemia." (PMID 40405527, 2025). "Our data demonstrate that the 9p21.3 murine orthologous locus is activated in myocardial ischemia, and it regulates the Cdkn2a/b expression in response to myocardial ischemia, but without effects on the survival or the severity of the cardiac pathology." (PMID 40405527, 2025).
myoepithelial carcinoma (1 paper, 2022). "Bi-allelic loss of CDKN2A was seen in seven cases (SDC, MEC and AciCC two cases each and one myoepithelial carcinoma case)." (PMID 36077692, 2022).
myoepithelial tumor (1 paper, 2017). A benign or malignant tumor characterized by the presence of cells that show myoepithelial differentiation. "Thus, as in other myoepithelial tumors, loss of CDKN2A may contribute to malignant transformation in a small subset of MECAs." (PMID 29084941, 2017).
myopia (1 paper, 2025).